SKA1 (spindle and kinetochore associated complex subunit 1)
Description:
Component of the SKA complex, a microtubule plus end-binding complex of the outer kinetochore that stabilizes spindle microtubule-kinetochore attachments, promotes alignment of chromosomes at the mitotic spindle equator (chromosome congression) and assists suppression of the spindle assembly checkpoint. Kinetochores, consisting of a centromere-associated inner segment and a microtubule-contacting outer segment, play a crucial role in chromosome segregation by mediating the physical connection between centromeric DNA and spindle microtubules. The outer kinetochore is made up of the ten-subunit KMN network complex, comprising the MIS12, NDC80 and KNL1 complexes, and auxiliary microtubule-associated components such as the SKA complex; together they connect the outer kinetochore with the inner kinetochore, bind microtubules, and mediate interactions with mitotic checkpoint proteins that delay anaphase until chromosomes are bioriented on the spindle. The SKA complex is loaded onto bioriented kinetochores and it facilitates chromosome congression by stabilizing microtubules together with MAPRE1, and end-on attachment of the NDC80 complex to depolymerizing spindle microtubules, thereby assisting the poleward-moving kinetochore in withstanding microtubule pulling forces. The complex associates with dynamic microtubule plus-ends and can track both depolymerizing and elongating microtubules. The complex recruits protein phosphatase 1 (PP1) to the kinetochore in prometaphase and metaphase, to oppose spindle assembly checkpoint signaling and promote the onset of anaphase. In the complex, it mediates interactions with microtubules. It also stimulates AURKB/Aurora B catalytic activity. During meiosis the SKA complex stabilizes the meiotic spindle and is required for its migration to the cortex (By similarity).
Synonyms: C18orf24; MGC10200
Tractability: PROTAC: ubiquitination databases record sites on it.
Gene: Protein-coding gene on chromosome 18 (50,375,017 to 50,394,176, forward strand). Ensembl gene ENSG00000154839.
Subcellular location: Cytoplasm, cytoskeleton, spindle; Chromosome, centromere, kinetochore; Cytoplasm, cytoskeleton, microtubule organizing center, centrosome
Subcellular location (Human Protein Atlas): Microtubules; Primary cilium; Basal body; Centriolar satellite; Cytokinetic bridge
Pathways (Reactome):
Cell Cycle: Amplification of signal from unattached kinetochores via a MAD2 inhibitory signal; EML4 and NUDC in mitotic spindle formation; Mitotic Prometaphase; Resolution of Sister Chromatid Cohesion; Separation of Sister Chromatids
Signal Transduction: RHO GTPases Activate Formins
Gene Ontology:
Molecular function: microtubule binding; protein binding
Biological process: attachment of mitotic spindle microtubules to kinetochore; metaphase chromosome alignment; mitotic cell cycle; mitotic metaphase chromosome alignment; mitotic sister chromatid segregation; negative regulation of mitotic spindle assembly checkpoint signaling; positive regulation of microtubule polymerization; regulation of microtubule polymerization or depolymerization; chromosome segregation; establishment of meiotic spindle orientation; spindle assembly involved in female meiosis; cell division; nuclear chromosome segregation; nuclear division
Cellular component: centrosome; kinetochore; microtubule cytoskeleton; mitotic spindle; mitotic spindle microtubule; outer kinetochore; SKA complex; spindle microtubule; cytosol; meiotic spindle; spindle
Genetic constraint (gnomAD): Loss-of-function variants: 8 observed, 17 expected, observed/expected ratio (o/e) 0.47, 90% interval 0.28 to 0.85. The upper end of that interval is the gene's LOEUF score, 0.85, which puts it in group 3 of 6, group 1 being the genes least tolerant of losing a copy. Missense variants: 166 observed, 201.36 expected, observed/expected ratio (o/e) 0.82, 90% interval 0.73 to 0.94. Synonymous variants: 58 observed, 64.86 expected, observed/expected ratio (o/e) 0.89, 90% interval 0.72 to 1.11.
Homologues: Orthologues: chimpanzee SKA1 (99% identical), macaque SKA1 (96% identical), pig SKA1 (87% identical), dog SKA1 (85% identical), rabbit SKA1 (85% identical), guinea pig SKA1 (80% identical), rat Ska1 (80% identical), mouse Ska1 (75% identical).
Diseases named in the same sentence as SKA1 in open-access papers:
SKA1 is named in the same sentence as 36 diseases in open-access papers, as found by Europe PMC text mining. Sharing a sentence is not in itself a finding about the gene and the disease. The quoted sentences say what the papers report.
hepatocellular carcinoma (13 papers, 2015 to 2025). A malignant tumor that arises from hepatocytes. "Kaplan–Meier (K–M) survival curve analysis and time-”ependent ROC curve analysis were used to evaluate SKA1’s prognostic and diagnostic value in hepatocellular carcinoma." (PMID 37746945, 2023). "Second, we grouped 373 instances of hepatocellular carcinoma into distinct subgroups according to clinical and pathological criteria and conducted subgroup K–M survival curve analysis to further analyze the association between SKA1 expression and survival." (PMID 37746945, 2023). "Additionally, we further investigated the underlying mechanism of SKA1 overexpression in Hepatocellular Carcinoma, and our data showed that SKA1 overexpression may be related to its DNA hypomethylation." (PMID 37746945, 2023). "LncRNA MRVI1-AS1 was found to accelerate hepatocellular carcinoma progression by recruiting the RNA-binding protein CELF2 to stabilize SKA1 mRNA." (PMID 39194582, 2024). "In human hepatocellular carcinoma, SKA1 is involved in various pathways, including the Fanconi anemia pathway, homologous recombination pathway, spliceosome pathway, DNA replication, and cell cycle signaling pathway." (PMID 37814813, 2023). "Higher expression of SKA1 was also found to be significantly correlated with poor prognosis in hepatocellular carcinoma (HCC)." (PMID 35095717, 2021). "Several studies have documented that SKA1 plays an important role in the growth and proliferation of a variety of cancers, such as hepatocellular carcinoma, gastric cancer and non-small cell lung cancer." (PMID 34993016, 2021). "An immunohistochemical study of 126 hepatocellular carcinoma patients revealed that SKA1 expression is significantly elevated in tumor tissues, and it can regulate the hepatocellular carcinoma cell cycle and contributes to poor prognosis." (PMID 33224872, 2020). "Inhibition of SKA1 led to cell cycle arrest and apoptosis in a number of tumors including hepatocellular carcinoma, non-small cell lung carcinoma and gastric cancer." (PMID 31827398, 2019). "However, the potential clinical applications of SKA1–3, particularly in hepatocellular carcinoma (HCC) prognosis and progression, have completely unknown yet." (PMID 36439516, 2022). "Specifically, lncRNA MRVI1-AS1 enhances SKA1 expression in hepatocellular carcinoma by binding to the RNA-binding protein CELF2, thereby facilitating its interaction with the downstream target gene SKA1 mRNA, which stabilizes SKA1 and activates its expression." (PMID 40861273, 2025). "In addition, SKA1 is a critical factor that plays an essential role in the regulation of hepatocellular carcinoma cell proliferation and apoptosis; research showed that knockdown of SKA1 inhibited hepatocellular carcinoma cell proliferation by inducing cell cycle arrest in the G0/G1 phase." (PMID 26063960, 2015). "Increasing clinical evidence has indicated that poor clinical prognosis, tumor invasion, and metastasis are all connected to increased SKA1 expression in a wide variety of cancers, including non-small cell lung cancer, bladder cancer, and hepatocellular carcinoma." (PMID 37814813, 2023).
non-small cell lung carcinoma (7 papers, 2018 to 2023). A group of at least three distinct histological types of lung cancer, including non-small cell squamous cell carcinoma, adenocarcinoma, and large cell carcinoma. "SKA1 is also reported to be involved in chemo-resistance and contributes to cisplatin resistance in non-small cell lung carcinoma cells by protecting tumor cells from cisplatin-induced cell apoptosis." (PMID 31827398, 2019). "SKA1 overexpression has been observed in gastric cancer, oral adenosquamous carcinoma, prostate cancer, papillary thyroid carcinoma, non-small cell lung cancer, and salivary adenoid cystic carcinoma." (PMID 30537941, 2018). "Of MMPs, MMP2 and MMP9 were the main members presented to be regulated by SKA1 and TRPV2 in some cancers, such as human adenoid cystic carcinoma, non-small cell lung cancer and prostate cancer 20-22." (PMID 35813298, 2022). "Other studies showed that overexpression of SKA1 and SKA3 was related to cancer aggressiveness in several other cancers, including non-small cell lung cancer, prostate cancer, bladder cancer, gastric cancer, colorectal cancer and adenoid cystic carcinoma." (PMID 29928475, 2018). "It was also reported that high level of SKA1 was correlated with the progression and malignancy of non-small cell lung carcinoma (NSCLC), which also protects NSCLC cells from cisplatin-induced apoptosis." (PMID 34845974, 2021).
breast carcinoma (6 papers, 2021 to 2023). "Spindle and kinetochore-associated complex subunit 1 (SKA1) can promote oxaliplatin resistance in breast cancer cells by activating the Notch and Wnt pathways; inhibition of spindle and kinetochore-associated complex subunit 2/3 (SKA2/3) attenuates proliferation and migration of tumor cells." (PMID 35389773, 2022). "Immunohistochemistry demonstrated that the expression differences of SKA1/2/3 were significant between the breast cancer group and the paracancerous group." (PMID 37180139, 2023). "CircFAT1 facilitates oxaliplatin (OX) resistance in breast cancer by regulating miR-525-5p/SKA1, and the Notch and Wnt pathways can be activated by SKA1, which has been identified by rescue assays, GSEA, and western blotting." (PMID 35070998, 2021). "Notably, dysregulated expression of SKA1/2/3 was involved in the tumorigenesis and progression of multiple cancer types such as liver cancer, breast cancer, cervical cancer and other malignant tumors, which in turn can affect the prognosis of cancer patients." (PMID 37180139, 2023). "SKA1 is a hub gene related to the pathologic stage of breast cancer." (PMID 34993016, 2021). "In breast cancer, circFAT1 may regulate miR-525-5P/SKA1 resistance through Notch and Wnt pathways, providing a potential target for breast cancer treatment." (PMID 35003269, 2021). "Therefore, we speculate that SKA1 may be involved in the adverse development of breast cancer, especially HER2-positive BC, which is worthy of further study." (PMID 34845974, 2021). "SKA1 and SKA3 genes are immunotherapy-related biomarkers in breast cancer and breast cancer stem cells." (PMID 34993016, 2021).
gastric cancer (6 papers, 2015 to 2021). A primary or metastatic malignant neoplasm involving the stomach. "The few studies on this indicate that abnormal SKA1 expression might be closely associated with the development of other solid tumors, such as gastric cancer, oral adenosquamous carcinoma, and neuronal glioblastoma." (PMID 26063960, 2015). "Depletion of SKA1 inhibited cell proliferation in gastric cancer by blocking cell cycle in S phase." (PMID 30564062, 2018).
adenoid cystic carcinoma (4 papers, 2018 to 2022). A malignant tumor arising from the epithelial cells. "SKA1 knockdown inhibited cell proliferation, invasion, migration, and cell cycle arrest in human adenoid cystic carcinoma." (PMID 36439516, 2022).
pancreatic ductal adenocarcinoma (4 papers, 2020 to 2022). An infiltrating adenocarcinoma that arises from the epithelial cells of the pancreas. "High SKA1 expression was significantly correlated with tumor size, cellular differentiation, and a poor prognosis in pancreatic ductal adenocarcinoma." (PMID 36439516, 2022). "High level of SKA1 contributed to the proliferation, migration, and metastasis of pancreatic ductal adenocarcinoma cells and reflected poor overall survival." (PMID 34845974, 2021). "As a tumor promoter of pancreatic ductal adenocarcinoma, SKA1 overexpression promoted tumor proliferation and migration in vivo and vitro through inhibiting G2/M arrest and regulating actin cytoskeleton organization by activating Cdc426." (PMID 34845974, 2021). "Joint-effect survival analysis of SKA1 expression and clinical variables in pancreatic ductal adenocarcinoma patient overall survival." (PMID 33224872, 2020). "SKA1 expression was detected in 145 pancreatic ductal adenocarcinoma (PDAC) specimens by immunohistochemistry." (PMID 32232899, 2020). "In addition, SKA1 in pancreatic ductal adenocarcinoma acts as a tumor promoter, and SKA1 overexpression promoted cell proliferation, migration, and invasion in vitro and in vivo." (PMID 36439516, 2022).
prostate carcinoma (4 papers, 2018 to 2022). A carcinoma that arises from epithelial cells of the prostate gland. "Moreover, overexpression of SKA1 has also been found in gastric, oral and prostate cancer, and can promote cancer cell proliferation and colony formation in these malignancies." (PMID 30537941, 2018). "Moreover, SKA1 silencing also induces cell apoptosis in prostate cancer and oral adenosquamous carcinoma, suggesting SKA1 may be involved in the apoptotic resistance in cancer." (PMID 30537941, 2018).
renal cell carcinoma (4 papers, 2018 to 2022). "SKA1 was identified as the target of antitumor mir-10a-5p in renal cell carcinoma (RCC) and overexpression of SKA1 was associated with poor prognosis of patients with RCC." (PMID 34845974, 2021). "The MAPK phosphatase family member dual-specificity phosphatase 6 (DUSP6), may be a crucial effector for SKA1-mediated malignant progression of renal cell carcinoma based on the degree of connection between cancer cell motility and target genes, p-value, and fold change." (PMID 36462498, 2022).
esophageal squamous cell carcinoma (3 papers, 2022). Esophageal squamous cell carcinoma (ESCC) is a type of esophageal carcinoma (EC) that can affect any part of the esophagus, but is usually located in the upper or middle third. "SKA1 was found to be significantly overexpressed in esophageal squamous cell carcinoma cells, and suppression of the SKA1 expression could significantly inhibit the cell cycle progress, cell migration and proliferation, and promote the cell apoptosis." (PMID 36439516, 2022). "Knockdown of ETV5 or its downstream genes SKA1 and TRPV2 significantly suppress Esophageal squamous cell carcinoma cells migration and invasion, respectively." (PMID 36052230, 2022).
glioma (3 papers, 2019 to 2021). A benign or malignant brain and spinal cord tumor that arises from glial cells (astrocytes, oligodendrocytes, ependymal cells). "An in vitro study found that SKA1 accelerates cell proliferation and cancer progression in glioma via tumor-associated signaling pathways, including cell cycle and Wnt/β-catenin signaling." (PMID 33224872, 2020). "GSEA analysis of both RNA-seq and microarray dataset indicated that genes involved in Wnt/β-catenin signaling were enriched in glioma tissues with high expression of SKA1." (PMID 31827398, 2019). "SKA1 promotes malignant phenotype and progression of glioma via multiple pathways, including cell cycle, EMT, Wnt/β-catenin signaling pathway." (PMID 31827398, 2019). "Herein, we investigated the precise role of SKA1 in the progression and malignant phenotype of human glioma." (PMID 31827398, 2019). "Since Wnt/β-catenin signaling pathway is involved in stemness and proliferative potential in several cancers, further work is needed to unravel potential involvement of SKA1 in glioma stemness." (PMID 31827398, 2019). "The median PFS of glioma patients with higher and lower expression of SKA1 was 10.27 months and 38.47 months, respectively (P < 0.0001)." (PMID 31827398, 2019). "In brief, analysis of public dataset revealed that SKA1 expression was positively correlated with glioma grade in mRNA level." (PMID 31827398, 2019). "Results showed that expression level of E-cadherin and Claudin was increased, and that of N-cadherin, PLOD2, MMP2 and Snail was significantly decreased after SKA1 knockdown in glioma cells." (PMID 31827398, 2019). "The results of colony forming assay performed in U87, U251, LN229 and T98 glioma cells further confirmed that suppression of SKA1 expression attenuated cell viability and proliferation of glioma cells in vitro." (PMID 31827398, 2019). "Western blot was performed to analyze the expression of SKA1 in clinical samples and signaling pathway proteins in glioma cells, respectively." (PMID 31827398, 2019). "In conclusion, SKA1 expression increased along with advances of glioma grades, and SKA1 is a potential biomarker of poor prognosis for glioma." (PMID 31827398, 2019). "In the present study, we identified SKA1 as a potential biomarker of malignant phenotype for glioma and confirmed that SKA1 expression increased along with advances of glioma grades." (PMID 31827398, 2019). "Moreover, the overexpression of SKA1 and SKA3 was significantly associated with poor prognosis of patients with gliomas." (PMID 35095717, 2021). "Furthermore, high mRNA levels of SKA1 and SKA3 complex were significantly associated with shorter OS of patients with glioma." (PMID 35095717, 2021). "Considering these results, SKA1 could a promising therapeutic target for the treatment of human glioma." (PMID 31827398, 2019). "We further clarified that SKA1 was involved in Wnt/β-catenin signaling pathway and could be a potential biomarker of malignant phenotype in glioma." (PMID 31827398, 2019). "Particularly, SKA1 promotes proliferation, migration and invasion abilities in glioma cells." (PMID 31827398, 2019). "Additionally, Boyden assay revealed that SKA1 knockdown significantly suppressed the invasion of glioma cells." (PMID 31827398, 2019). "Here, we confirmed that expressions of SKA1 increased along with advances in glioma grades." (PMID 31827398, 2019). "Furthermore, immunochemistry staining for the proliferation marker, PCNA, indicated that suppression of SKA1 significantly inhibited glioma proliferation in vivo." (PMID 31827398, 2019). "Considering that SKA1 was overexpressed in grade IV glioma, we used Chinese Glioma Genome Atlas (CGGA) dataset to determine whether SKA1 could be used as a biomarker to distinguish between GBM and non-GBM patients (Grade II and III)." (PMID 31827398, 2019). "SKA1 expression is positively correlated with glioma grade and could be a promising biomarker for GBM." (PMID 31827398, 2019).